ARF6 (ARF GTPase 6)
Diseases named in the same sentence as ARF6 in open-access papers (continued):
Sharing a sentence is not in itself a finding about the gene and the disease.
cancer (continued). "Finally, we address the potential therapeutic strategies against malignant tumors that target this signaling pathway to promote ARF6 activity." (PMID 37834383, 2023). "Indeed, the pattern of AMAP1 overexpression among cancers is similar to that of ARF6 overexpression." (PMID 37158894, 2023). "Moreover, it is previously reported that ARF6 has important effects on proliferation, angiogenesis, invasion, and metastasis, microvesicle formation in various cancers." (PMID 37716993, 2023). "Therefore, ARF6 and its effectors play pivotal roles in cancer progression and are potential novel biomarkers and drug targets for malignant cancers." (PMID 37834383, 2023). "Thus, the ARF6-based pathway also extrinsically plays an essential role in vascular endothelial cells and is involved in the pathogenesis of malignant tumor progression." (PMID 37834383, 2023). "Analysis of the precise molecular mechanisms of how the ARF6 pathway, which confers mesenchymal properties, contributes to drug resistance may be important in the development of cancer therapeutic strategies." (PMID 37834383, 2023). "Pharmacological inhibition of guanine nucleotide exchange on Arf6 using SencinH3 or NAV2729 has been used successfully to reduce levels of activated Arf6-GTP in cancer cells and could be a potential therapy for IQSEC2 disease." (PMID 36902414, 2023). "ADP-ribosylation factor 6 (ARF6) is a fellow of the RAS superfamily, which encodes a small guanine nucleotide-binding protein (GTP-binding protein) involved in the regulation of cancer cell invasion, metastasis and proliferation." (PMID 37580745, 2023). "The ARF6-mitochondria link appears to be important for cancer cell invasion and metastasis." (PMID 37158894, 2023). "ARF6 mRNA expression was then compared between the same tissues from healthy and cancer patients." (PMID 35143561, 2022). "In the UTUC panorama, the mechanism by which ARF6 modulates the migration and aggression of the cancer cells in the urothelium district remains unknown." (PMID 35269744, 2022). "In addition to ARF6, ARF regulators (ARF GEFs and GAPs) have also been associated with the invasion and metastasis of cancer cells." (PMID 35143561, 2022). "The ARF6 gene expression levels are highly variable between healthy and cancer tissues." (PMID 35143561, 2022). "ARF6 (GAPs), such as SMAP1, AMAP1 and GIT1, are also linked to cancer progression." (PMID 35143561, 2022). "Arf6 is also involved in facilitating cancer cell migration and invasion." (PMID 36017701, 2022). "Although there are several studies on linking ARF6 to cancer, particularly in invasion and migration behaviours crucial for metastasis, there is a dearth of data concerning the expression of ARF6 in cancers over a wide range of tissue." (PMID 35143561, 2022). "In addition, the available evidence indicated that ARF6 acted as an oncogene in many cancers to promote the proliferation invasion, and migration of cancer cells." (PMID 35899235, 2022). "Notably, the Arf6 isoform has been described as an important mediator of cancer cell migration and invasion." (PMID 33673086, 2021). "In that context, blocking both the internalization and trafficking of receptors, as well as their signaling through the combined inhibitory action on ARF6 and Ras, like Rasarfin does, may confer increased therapeutic advantages in some cancers." (PMID 34344896, 2021). "Recent studies have indicated that ARL4C could be induced by EGF and promotes the motility of cancer cells by remodeling actin cytoskeleton through Arf6 activation, which might be involved in the migration, invasion, and proliferation of cancer cells." (PMID 33194732, 2020). "Thus, Arf6 in pan-endothelial cells is a highly potential therapeutic target to prevent cancer progression." (PMID 28900118, 2017).
cancer (continued). "Thus, we clarified for the first time the novel physiological and pathological functions of Arf6 in LECs in vivo, providing the opportunity for a potential clinical application to anti-cancer treatment." (PMID 28900118, 2017). "Importantly, blocking Egfr or Arf6 suppresses Hh signalling and correspondingly inhibits overgrowth in both flies and human cancer cells." (PMID 28281543, 2017). "We found that Arf6-RNAi specifically reduced Arf6 protein levels and suppressed the growth of these cancer cells in comparison to cancer cells without oncogenic Ras mutations or cells treated with RNAi control." (PMID 28281543, 2017). "The contribution Arf6 makes to Ral dependent growth signalling in these cancers could also be different." (PMID 27269287, 2016). "Thus, while both Ral and Arf6 are anchorage-independent in these cancer cells their regulatory crosstalk is clearly different." (PMID 27269287, 2016). "ARF6, therefore, may be a potential cancer biomarker, however its role in prostate carcinogenesis has yet to be investigated." (PMID 26185744, 2015). "The Arf6 pathway mediates the motile and invasive phenotypes of cancers." (PMID 24621372, 2014). "AMAP1 is a downstream effector for Arf6, and functions in cancer invasion and metastasis." (PMID 21858086, 2011). "Our results suggested that Arf6 might be a predictive biomarker for the invasive phenotypes of primary cancers of the human breast." (PMID 19416474, 2009). "ARF6 may moreover promote cancer invasion and metastasis, and also acidosis and immune checkpoint." (PMID 37158894, 2023). "However, the concrete mechanism of ARF6 in regulating the proliferation of cancer cells, especially in HCC, remains unknown." (PMID 37716993, 2023). "Thus, the MVP may be crucial for promoting cancer cell invasion, metastasis, drug resistance, and PD-L1 recycling through the overexpressed ARF6 pathway activated by RTKs." (PMID 36408139, 2022). "Finally, we determined whether Arf6 similarly regulates Hh signalling in human cancer lines by examining changes in Gli1 expression levels following Arf6 RNAi knockdown." (PMID 28281543, 2017). "Specific inhibitors of Arf6 might provide a new cancer therapeutic opportunity." (PMID 28900118, 2017). "For example, the activation of Arf6 leads to the disassembly of adherens junctions through the internalization of E-cadherin, leading to changes in cell shape and motility, a process referred to as epithelial–mesenchymal transition, during wound healing and cancer invasion." (PMID 27622210, 2016). "ARF6, a relatively obscure member of the ADP‐ribosylation factor (ARF) family of small GTPases, has lately gained attention as a significant component in cancer biology." (PMID 40275490, 2025). "There have been articles summarizing the comprehensive functions of ARF6 in future cancer treatment, including ARF6-GEF, protein structure, and its role in cancer." (PMID 38617932, 2024). "This resulted in enhanced cancer cell proliferation and metastatic potential through activation of the ARF6-mediated Src/PI3K/Akt pathway, where ARF6 is a direct miR760 target." (PMID 39044824, 2024). "Here, the authors identify CNK2 as a key mediator of cancer cell motility, linking extracellular stimuli via AXL signalling and downstream activation of ARF6 GTPase, resulting in increased metastasis in preclinical models." (PMID 37322019, 2023). "Our series of studies demonstrated that ARF6 and its downstream effector AMAP1 are often overexpressed in different cancers, including PDAC, and this overexpression is statistically correlated with the poor prognosis of cancer patients." (PMID 37834383, 2023). "ADP-ribosylation factor 6 (ARF6) and AMAP1 are often overexpressed in cancers, which statistically correlates with poor outcomes." (PMID 37834383, 2023). "Our present study suggests that Arf6-based signaling pathways play an important role in the acquisition of invasive and metastatic traits via EMT induction in cancer cells." (PMID 36408139, 2022).
cancer (continued). "A series of our studies have identified that the small GTPase ARF6 and its downstream effector AMAP1 (also called ASAP1/DDEF1) are often overexpressed in different cancers, including PDAC, and closely correlate with poor patient survival." (PMID 34001163, 2021). "ARF6 belongs to the small GTPase ARF family and has well-documented roles in promoting cancer cell invasion, migration and proliferation in various types of tumors." (PMID 34621682, 2021). "To further explore the antilung cancer mechanism of ZSD, we conducted Human Signal Transduction Pathway Finder PCR Array and found that TRAIL, glypican, IL-3-mediated signaling, Arf6 and mTOR signaling, and PI3K/AKT signaling pathway were mainly enriched." (PMID 33777320, 2021). "A series of our studies demonstrated that ARF6 and one of its downstream effectors, namely, AMAP1 (also called DDEF1 and ASAP1), constitute the core signaling machinery that drives cancer malignancy and therapeutic resistance when ARF6 is activated." (PMID 32580737, 2020). "Expression levels of Arf6 and AMAP1 are highly correlated with the invasive activities of cancer cells, and these proteins promote the recycling back of internalized β1-integrins to the plasma membrane during cancer invasion." (PMID 29992963, 2018). "We previously showed that the small GTPase Arf6 and its effector AMAP1, which are frequently overexpressed in cancers, have crucial roles in cancer invasion, metastasis, and also drug resistance." (PMID 29992963, 2018). "In this study, the expression levels of ARF6 and ARF5 in the serum of CRC patients were significantly reduced after exercise, reflecting the positive intervention effect of acute aerobic exercise on cancer patients." (PMID 40270615, 2025). "The release of ectosomes is regulated by small Rab GTPases, including Rho-associated coiled coil-containing protein kinase and the GTP-binding protein ADP-ribosylation factor 6 (ARF6), which have been identified as positive regulators of vesicle budding in cancer cells." (PMID 38570784, 2024). "In cancer cells, it has been shown that activation of ARF6 (ADP-Ribosylation Factor 6), ADP Ribosylation Factor 1 (ARF1), and small GTP-binding proteins lead to phosphorylation of the myosin side chain of myosin and contraction of actomyosin, permitting MV to detach from the membrane." (PMID 37781539, 2023). "Although alterations in the expression levels of ARF6 have been reported in several cancers, an overall view of ARF6 gene expression in healthy and cancer tissues has been lacking." (PMID 35143561, 2022). "In contrast, inhibition of MVP is ineffective when cancer cells do not overexpress components of the ARF6-based pathway." (PMID 36408139, 2022). "As Arf6 is required for the formation of invadopodia and for the targeting of MMPs from intracellular compartments to the plasma membrane, we hypothesize that by inhibiting Arf6 activation, CTC would inhibit the invasive properties of cancer cells." (PMID 33673086, 2021). "We further found that Pals1 prevents cancer cell metastasis by controlling Rac1-dependent cell migration through inhibition of Arf6, which is independent of the canonical binding partners of Pals1." (PMID 33941200, 2021). "ARF6 and AMAP1 proteins are often abnormally overexpressed in different types of cancers, including breast cancer, renal cancer, lung adenocarcinoma, head and neck cancer and PDAC, to be statistically correlated with the rapid recurrence and poor overall survival of patients." (PMID 32580737, 2020). "Recent studies including the results from our laboratory showed that Arf6 activation could be induced by EGF and act as a mediator of cell migration and invasion in various types of cancer cells." (PMID 25779663, 2015). "In addition, JIP3 knockdown, which also acts downstream of ARF6, increased migration rates in non-malignant and cancer cells." (PMID 39217195, 2024).
cancer (continued). "However, we found a number of established drivers of cancer progression and invasion (e.g., mTOR, STAT1/5, RHOC, ARF6, HMGB, and CRK) with increased expression levels as well as known suppressors (e.g., AIFL1 and SLIT3) with decreased expression levels upon PTEN inhibition." (PMID 36555834, 2022). "This indicates that Arf6 does not directly involve in MV biogenesis in some cancer cells." (PMID 33473262, 2021). "Although GIT1 is associated with several types of cancer, it is not clear whether ARF6 inactivation by GIT1 is a requirement for cancer progression." (PMID 32426352, 2020). "Similarly to MVs, they express ARF6 and originate directly from plasma membrane budding, but LOs are nonapoptotic membrane blebs that shed from aggressive cancer cells." (PMID 31281356, 2019). "Because Arf6 has been identified to play an important role in cancer cell migration and the PH domain of GEP100 links EGFR signaling to Arf6 activation, it is worthwhile to explore whether the PH domain of GEP100 is involved in EGF-induced Arf6 signaling pathway and cancer cell migration ability." (PMID 22701712, 2012). "Indeed, ARF6 mRNA levels do not necessarily correlate with ARF6 protein levels in cancer cells." (PMID 37158894, 2023). "We were particularly interested in studying ARF6, which was a member of small GTPases ADP-ribosylation factor family, and its downstream effector AMAP1 have been reported overexpressed in several types of cancer and could promote cancer cell proliferation, invasion and migration." (PMID 33028329, 2020). "Therefore, this Arf6 pathway appears to be specific to some cancer cells, and may not normally be used in normal cells." (PMID 24621372, 2014). "The cancer promoting effects of ARF1, ARF3, ARF4 and ARF6 in individual cancers have been studied, only the role of ARF5 in cancer has not been reported." (PMID 38617932, 2024). "While further work is required to determine if, and how, the CNKSR2 locus is derepressed in non-neuronal cancer cells, our study suggests that aberrant expression of CNK2A confers a motile phenotype by hijacking ARF6 signalling." (PMID 37322019, 2023). "We then performed immunohistochemical analysis and confirmed that Arf6 and AMAP1 are expressed at high levels in cancer cells rather than in stromal cells." (PMID 29329590, 2018). "Although a cross-talk between signaling from Arf6, ERK and Rac1 may occur in different cellular processes, the precise molecular mechanisms implicating GEP100 in cancer cell motility have not yet been unraveled." (PMID 22701712, 2012).
infection (29 papers, 2012 to 2025). The state of being infected such as from the introduction of a foreign agent such as serum, vaccine, antigenic substance or organism. "Arf6 is important for the internalization and recycling of MHC-I and integrins and affects the internalization of Coxsackievirus A9: Arf6 siRNA slightly inhibits infection, but the overexpression of Arf6-T27N caused an 85% reduction in infection." (PMID 31060328, 2019). "The USP activity of TRE17 was required to rescue both ARF6 and associated cargo from SE retention in infection." (PMID 30042195, 2018). "Taken together, these findings suggest that infection not only alters ARF6 dynamics and the associated cargos but also influences sorting events in a cargo-specific manner." (PMID 30042195, 2018). "Further analysis determined that the major regulator of CIE, ARF6, is itself dysregulated by infection; ARF6 showed an increased association with SEs, resulting in enlarged ARF6-EEA1-positive structures." (PMID 30042195, 2018). "To determine if infection alters the frequency of this association, we analyzed ARF6 and EEA1 localization under steady-state conditions in both uninfected and HCMV-infected cells." (PMID 30042195, 2018). "However, our study also revealed that the contribution of Arf1 and Arf6 is most likely associated with the earliest stages of infection, either during virion entry or during the establishment of infection." (PMID 34440611, 2021). "However, our study also revealed that the contribution of Arf1 and Arf6 is most likely associated with the earliest stages of infection, either in terms of virion entry or the establishment of infection." (PMID 34440611, 2021). "Also, ARF6-associated membranous organelle functions undergo significant changes at later stages of infection." (PMID 33042998, 2020). "Second, we showed that the ability of TRE17 to mediate ARF6 trafficking (and, therefore, CIE trafficking) is dependent on its USP activity, as expression of the TRE17 USP mutant in infection resulted in retention not only of ARF6 at the SE but also of its associated cargo." (PMID 30042195, 2018). "Importantly, as Rab GAP deficient EspG is able to interact with ARF6, but unable to disrupt recycling, the functional disruption of REs during infection appears to be dependent on EspG's Rab GAP activity." (PMID 27261256, 2016). "ADP-ribosylation factor 6 (ARF6) has been described as a host factor for SARS-CoV-2 replication and is involved in the entry and infection of several pathogenic viruses." (PMID 37342971, 2023). "NAV-2729 showed a dose-dependent inhibition of infection, suggesting that ARF6 is an important factor for SARS-CoV-2 infection in Huh-7." (PMID 37342971, 2023). "In our investigation, we extended studies regarding the importance of ARF6 to the infection of other cell types – kidney organoids and Calu3 cells, a model of respiratory epithelial cells." (PMID 37342971, 2023). "Three genes, Nitab4.5_0003119g0050 (ARF2), Nitab4.5_0000315g0090 (ARF6), and Nitab4.5_0002071g0010 (ARF6), were highly expressed in the early stage of infection." (PMID 38057713, 2023). "Immunofluorescence studies of HCMV and MCMV showed excessive recruitment of Arf6 to the membrane units within the inner AC, beginning early in infection." (PMID 36077391, 2022). "ARF6 is involved in the invasion of host cells by Salmonella enterica serovar Typhimurium, which facilitates the establishment of intracellular infection." (PMID 36094311, 2022). "The signal of Arf6 cytoplasmic staining was increased, likely due to the cell contraction and the increasing time of infection coalesced to the juxtanuclear area." (PMID 34440611, 2021). "Altogether, these data suggest that Arf1 and Arf6 are essential for the establishment of infection in the steps before the MCMV genome enters into the nucleus." (PMID 34440611, 2021).